HIF1A (hypoxia inducible factor 1 subunit alpha)
Diseases named in the same sentence as HIF1A in open-access papers (continued):
Sharing a sentence is not in itself a finding about the gene and the disease.
tumor (continued). "Previous studies indicated that most HIF-1α protein would be degraded by the von Hippel–Lindau tumor suppressor under normoxic conditions, while a few HIF-1α protein would escape from the degradation with the help of a series of protective proteins." (PMID 36864422, 2023). "Quantitative analysis further demonstrated that HIF-1α expression was significantly higher in tumor tissues than in normal tissues; however, HIF-1α was rarely expressed in high-grade OSCC tissues compared to that in low-grade OSCC tissues." (PMID 37095487, 2023). "Tumor hypoxia can also induce metabolic reprogramming of fatty acid (FA) metabolism, through which HIF-1α plays an essential role in diminishing fatty acid β-oxidation (FAO) in hypoxic cancer cells." (PMID 38066600, 2023). "HIF‐1α is considered to be a master transcriptional regulator of the tumor cell response to hypoxia." (PMID 36703877, 2023). "Infiltration of myeloid-derived suppressor cells (MDSCs) in tumour sites under hypoxia via the HIF-1α pathway was significantly reduced in treated tumours." (PMID 36656411, 2023). "Alternatively, inhibition of this pathway reduced radiotherapy-induced tumor angiogenesis, indicating the importance of the HIF-1α/VEGF pathway for radiation-related stimulation of vascular growth." (PMID 37849740, 2023). "CoQ10 reduces HIF-1α, p-Akt, and NF-κB levels, regulating the processes of tumor neovascularization, inflammation, and tumor cell invasion." (PMID 36319818, 2023). "HIF-1α is a protein ubiquitously expressed and notably produced by tumor cells under hypoxic conditions." (PMID 37511605, 2023). "HIF-1α is known for tumour suppressor functions, and HIF-2α has been reported to promote tumorigenicity in ccRCC." (PMID 37174052, 2023). "As a key regulator of tumor hypoxia, HIF-1α is commonly highly expressed in solid tumors and is closely related to treatment failure and poor prognosis." (PMID 36675491, 2023). "IHC staining utilizing both NLRP3 antibody and HIF-1A antibody further confirmed the tumor cells with elevated HIF-1A showed enhanced inflammasome in its microenvironment." (PMID 36720864, 2023). "Adaptation to hypoxic conditions is achieved primarily through excessive accumulation of HIF-1α in tumor cells." (PMID 37190124, 2023). "Like other immune cells that are suppressed by the TME, mechanisms that inhibit NK cell activity are postulated to be due to HIF-1α expression, which will decrease under a situation where tumor vascular normalization is achieved." (PMID 37631236, 2023). "Hypoxia impacts the tumor growth, progression, and angiogenesis mainly through the transcriptional factor HIF-1α." (PMID 36908706, 2023). "The previous study shows that SIRT3 mediates metabolic reprogramming by promoting the degradation of HIF‐1α and functions as a tumour suppressor by suppressing the production of reactive oxygen species (ROS) and regulating HIF‐1α." (PMID 36383055, 2023). "In sharp contrast, elevated expression of HIF-1α reduced tumor size whereas HIF-1α knockdown increased cell proliferation." (PMID 36831657, 2023). "HAUSP (USP7) deubiquitinates HIF-1α to induce tumor epithelial–mesenchymal transition and metastasis." (PMID 37190313, 2023). "Unlike PINK1, the downstream Parkin has been reported to inhibit tumor angiogenesis through ubiquitination degradation of HIF-1α at lysine 477, and inhibiting JAK2/STAT3/VEGF pathways in osteosarcoma." (PMID 37407961, 2023). "The activated HIF1-α in tumor tissue upregulates the activity of metabolic enzymes or proteins and enhances metabolic pathways such as glycolysis." (PMID 37403048, 2023). "It has been reported by some previous researchers that HIF-1α plays an important role in triggering the glycolysis of tumor cells and enhancing their 18F-FDG uptake." (PMID 36980323, 2023).
tumor (continued). "ECA has been found to inhibit the HIF pathway by downregulating the mRNA expression of VEGF, a downstream target gene of HIF-1a, in HeLa cells under hypoxia, thereby inhibiting tumor angiogenesis and metastasis." (PMID 37047688, 2023). "Functional and mechanistic investigations have corroborated that ENO2 is transcriptionally activated by HIF-1α, and it orchestrates tumor cell glycolysis to sustain the energy supply and promote the progression of ccRCC." (PMID 37760940, 2023). "Due to the activation of HIF‐1α‐dependent increase of arginine (Arg) activity and nitric oxide (NO) generation, tumor-derived MDSCs have recently been shown to be highly immunosuppressive." (PMID 37735675, 2023). "Changes in expression pattern after neoadjuvant chemoradiotherapy described in this study support the concept of tumor reoxygenation, changes in HIF-1α-dependent signaling, and indicate activation of the DNA damage response pathway." (PMID 37296922, 2023). "These authors observed a positive correlation between HIF1A overexpression and the more aggressive tumor phenotype of various human cancers." (PMID 38273861, 2023). "HIF-1α can also mediate tumor cells’ adaptation to the hypoxic microenvironment, accelerate EMT, and increase resistance to radiotherapy/chemotherapy." (PMID 37046617, 2023). "Altered cell metabolism that results in tumor initiation and growth has received renewed attention, and a functional role for HIF-1α in metastasis has been described." (PMID 36614196, 2023). "In this study, we have demonstrated for the first time that the tumor tissue in PMP grows in hypoxic conditions increasing hypoxia markers such as HIF-1α." (PMID 36776312, 2023). "HIF-1α an established cellular response to hypoxia, supports cell survival in the hypoxic tumor micro-environment, but also operates during normoxia downstream of mTOR13 to promote angiogenesis, radio-resistance, and metastasis." (PMID 37684337, 2023). "The results showed that decreased expression levels of HIF-1α and PD-L1 were found in the tumour tissues after treatment with TH-302 and TH-302 NPs." (PMID 37993847, 2023). "The results have shown that the patients in Group 1 had higher levels of HIF-1α in normal tissue than in the tumor, while the individuals in Group 2 had exactly the opposite profile." (PMID 38273861, 2023). "Hypoxia-induced HIF1α expression in tumor-infiltrating lymphocytes (TILs) increases PD-1 expression as well." (PMID 38275827, 2023). "They found that DRD2 interacted with von Hippel-Lindau (VHL) in the nucleus, and competitive binding of DRD2 and HIF-1α to VHL resulted in reduced ubiquitination-mediated degradation of HIF-1α, enhancing the epithelial-mesenchymal transition of tumor cells." (PMID 37415171, 2023). "Our finding suggested that CHIP potentially played a tumor-suppressor role through HIF-1α degradation." (PMID 37201586, 2023). "Low-TLS density in the invading front and in inner tumor areas was related to high TB (p = 0.02 and 0.002, respectively), HIF1α (p = 0.003 and 0.01, respectively), and LDH5 expression (p = 0.003 and 0.007, respectively)." (PMID 36586079, 2023). "For instance, during hypoxia, EVs released from cancer cells are enriched in angiogenic factors, such as VEGF and hypoxia-inducible factor 1-alpha (HIF-1α) that promote angiogenesis and later tumour metastasis." (PMID 36830690, 2023). "The deregulation of glucose metabolism in tumor cells is predominantly mediated by oxygen-related transcription factors, such as the hypoxia-inducible factor 1α (HIF-1α)." (PMID 36594102, 2023). "For example, HIF1α expression induced by a hypoxic tumor microenvironment can inhibit NK cell activity, but inhibition of HIF1α or using Hif1α-/- NK cells has been shown to potentiate NK cell activity against tumors in in vitro and in vivo experiments." (PMID 37539051, 2023).
tumor (continued). "In renal cancer cells, COMMD5 decreases proliferation, improves differentiation, accelerates autophagic cell death, and lowers VEGF production through downregulating HIF-1α, ultimately inhibiting tumor angiogenesis." (PMID 36776284, 2023). "Celecoxib, a cyclooxygenase-2 (COX-2) inhibitor, has been demonstrated to have anti-tumor effects through impairing HIF-1α." (PMID 37460927, 2023). "While HIF1A acts as a tumor suppressor and is frequently lost through inactivating mutations/14q chromosome deletions, HIF2A acts as an oncogene promoting the expression of its target genes (VEGF, PDGF, CAIX Oct4, among others)." (PMID 37489462, 2023). "PKM2 is highly expressed in tumor cells and has been shown to promote late pro-inflammatory cytokines though its interaction with hypoxiainducible factor 1α (HIF-1α), and has a role as a critical mediator in inflammatory microenvironment of cancer." (PMID 36797689, 2023). "TIPARP directly targets HIF-1α and recruits E3 ubiquitin-protein ligase to promote the degradation and inactivation of HIF-1α to inhibit tumor growth." (PMID 37907864, 2023). "In fact, tumor-derived lactic acid induces M2-like polarization of TAMs in the presence of hypoxia-inducible factor 1α (HIF-1α) and histone lactylation." (PMID 37443711, 2023). "The release of ADAM10 induced by HIF-1α results in the cleavage of MICA/B ligands present on the surface of tumor cells." (PMID 38057843, 2023). "Although the transcriptional activity of HIF-1α is critical for supporting tumor growth, its contribution to the hypoxic TME is also detrimental to effector T-cell function." (PMID 37180129, 2023). "Cancer cell-derived lactate leads to HIF-1α-dependent polarization of TAMs towards a tumor-permissive M2 phenotype and induces vascular endothelial growth factor A (VEGFA) expression in TAMs." (PMID 37490147, 2023). "In general, the expression level of HIF1A in cells is very low, but it is highly expressed in tumor cells and participates in various biological processes of tumor cells." (PMID 37644107, 2023). "We also noted that these anti-inflammatory TAM markers correlated with HIF-1α, suggesting this TAM phenotype is linked with tumour hypoxic regions." (PMID 37324244, 2023). "HIF1α is a predominant transcription factor in development of hypoxia adaptation and tolerance in tumor cells." (PMID 37813876, 2023). "Hsa_circ_0000566 significantly inhibited OS tumor growth compared to the control; however, OS tumor size was recovered in the group co-transfected with sh-Hsa_circ_0000566 and HIF-1α." (PMID 37008055, 2023). "CD31 and CAIX expression data were available for all 22 tumour samples, whereas HIF-1α immunohistochemistry was performed in 21/22 (95%) cancers." (PMID 37166494, 2023). "STAT3 is a major transcription factor that induces HIF-1α in cancer-associated fibroblasts and also elicits VEGF production to favor tumor development." (PMID 37893079, 2023). "HIF1α is essential in tumour initiation and glucose metabolism reprogramming, while HIF2α regulates biosynthetic pathways such as lipid metabolism, ribosome biogenesis, and the transcriptional activity of numerous factors." (PMID 38136342, 2023). "The HIF-1α/VEGF signaling pathway is a key pathway for the induction of lymphangiogenesis by tumor cells." (PMID 37718440, 2023). "It is predominantly sensed by the transcription factor HIF-1α in malignant and stromal cells and induces a plethora of target genes that promote reprogramming of tumor and TME metabolism, as well as angiogenesis to adapt to the hypoxic environment." (PMID 36845555, 2023). "These cytokines attract inflammatory cells, and tumor cells gather once more at the tumor-stroma interface with TAMs and CAFs to produce NF-κB and hypoxia-inducible factor (HIF-1α), creating a microenvironment that can encourage tumor growth." (PMID 37598126, 2023). "In contrast, CDH1 and HIF1A levels were negatively correlated with most tumor-infiltrating immune cells." (PMID 37716978, 2023).
tumor (continued). "The detection of CAIX expression in PET imaging is potentially interesting for the assessment of tumor hypoxia because of its relatively high expression on the cell surface and its prolonged presence in hypoxic tissues, in contrast to HIF-1α protein." (PMID 36844199, 2023). "RNA-seq analysis of FT895-treated S462TY cells revealed changes in the transcriptome, particularly in the genes involved in pathways related to HIF-1α signaling, carbohydrate metabolism, as well as the tumor survival pathway." (PMID 38203448, 2023). "The effect of HIF-1α expression on in vivo tumor metastasis of OSCC cells was evaluated using lung metastasis model." (PMID 37095487, 2023). "Single-cell RNA sequencing of tumor infiltrating NK cells revealed that HIF-1α inhibition maintained the expression of activation markers and effector molecules, while preserving cytotoxic activity in hypoxic conditions." (PMID 36980629, 2023). "In preclinical studies, TPZ effectively inhibited tumor colony forming in vitro, especially in hypoxic cells and induced cell cycle arrest and apoptosis, as well as downregulating HIF-1a, CA-IX, and VEGF expression." (PMID 37626923, 2023). "As previously reported by Fang and colleagues, SCG2 alters angiogenesis and tumor growth by HIF-1α destruction and is able to stimulate wound healing in response to fasting." (PMID 37446282, 2023). "Treatment-induced downregulation of HIF-1α and NF-kB led to a complete remodeling of the tumor cells proteome and secretome, impacting angiogenesis, monocyte infiltration, and their differentiation into macrophages." (PMID 36319818, 2023). "The authors developed a mathematical model to unearth node proteins that regulate the metabolic phenotype and found that AMPK and HIF-1α are core regulatory loop molecules involved in tumour metabolism." (PMID 37108242, 2023). "This metabolic reorganization of tumor cells is regulated by various oncogenic proteins and tumor suppressors, including hypoxia-inducible factor (HIF-1α) transcription." (PMID 36709284, 2023). "Future studies are needed to examine the potential interplay between STING signaling and HIF-1α or STAT3 in tumor-infiltrating DCs." (PMID 36821379, 2023). "Sunet al. proved that TEAD1 can regulate the transcription of HIF1A and further promote tumor glycolysis." (PMID 37723874, 2023). "For example, in the hypoxic TME, MDSCs express hypoxia inducible factor 1α (HIF1α) which upregulates cell surface expression of PD-L1 in both MDSCs and tumor cells." (PMID 38275827, 2023). "Trichosanthes kirilowii seeds were documented as showing inhibitory activity on tumor cell growth by limiting NF-κB or HIF1α in vitro and in vivo." (PMID 36673369, 2023). "Under hypoxic conditions, hypoxia-inducible factor 1 α (HIF1α) is a major regulator that promotes tumor development and increases glycolysis." (PMID 37957150, 2023). "The HIF-1α signaling pathway is believed to play a significant role in advancing the progression of GC by facilitating tumor cell growth, promoting angiogenesis, inducing EMT, fostering resistance to therapy, and inhibiting programmed cell death." (PMID 37894443, 2023). "The ROS generation is elevated triggered by hypoxia and increases the stabilization and activation of HIF-1α in various tumor cells." (PMID 37752569, 2023). "While HIF-1α promotes malignant cell adaptability and proliferation, nuclear factor-kappa B (NF-kappa B) is essential for tumour initiation and survival." (PMID 36891273, 2023). "Employing 2D, 3D, and in vivo mouse model, we clearly demonstrate the effect of propranolol on important proteins (CAIX, HIF1α) influencing the tumor microenvironment, activation of apoptosis, growth of spheroids and migration abilities." (PMID 37446271, 2023). "In this process, activated hypoxia-inducible factor-1α (HIF-1α) plays a pivotal role in the adaptive response of tumor cells to changes in oxygen levels." (PMID 37946265, 2023).
tumor (continued). "Hypoxia induces the hypoxia-inducible factor-1α (HIF-1α) that regulates the transcription of at least 60 genes regulating tumor cell survival, growth, proliferation, tumor angiogenesis, invasion/metastasis, glucose metabolism, immune cell function." (PMID 37275901, 2023). "Among HIFs, HIF1α is the key protein for tumor survival, and its expression is tightly regulated in multiple steps." (PMID 36509142, 2023). "PKM is known to play an important role in the regulation of tumor glycolysis and is able to activate HIF-1α-dependent transcription of glycolytic enzymes." (PMID 37060505, 2023). "Several direct and indirect inhibitors of HIF-1α are already in preclinical and clinical development, which can limit HIF-1α related tumor growth, angiogenesis, and tumor progression in many solid human tumors, including OSCC." (PMID 36766555, 2023). "Hypoxia-inducible factor-1α (HIF-1α) is one key transcriptional factor released in response to hypoxia within a rapidly growing tumor." (PMID 36766555, 2023). "Taken together, tumor-infiltrating neutrophils from pancreatic OT mice exhibit a strong glycolytic profile with up-regulated HIF-1α." (PMID 36614196, 2023). "The high expression of hyaluronic acid (HA)-binding protein KIAA1199 has been reported to be positively correlated with tumor stage, overexpression of HIF-1α and upregulation of angiogenesis markers." (PMID 37646027, 2023). "In primary BCa samples, HIF-1α has been observed via nuclear HIF-1α immunostaining in a vast majority of tumor cells." (PMID 38085375, 2023). "NF-κB, which promotes the migration and invasion of tumor cells, is activated by HIF-1α under severe hypoxia." (PMID 37835592, 2023). "HIF-1α is overexpressed in hypoxic conditions and drives the expression of a pool of genes involved in the adaptation of tumour cells to a hypoxic milieu supporting also the ability of cancer cells to escape treatment toxicity." (PMID 37407979, 2023). "Upon hypoxia, COUP-TF1 and HIF1α were shown to induce the expression of p27 and quiescence in tumour cells." (PMID 36701089, 2023). "The functional polarization of TAMs and tumor development in vivo are greatly influenced by PI3K/HIF-1α signaling-induced glycolysis-cholesterol metabolic axis, including glycolysis and enhanced cholesterol excretion." (PMID 37828561, 2023). "On the one hand, HIF-1α can promote the carcinogenic effects of CAFs, such as promoting tumor growth, while block other carcinogenic functions, such as tumor invasion and metastasis." (PMID 36906534, 2023). "Genetic ablation of HIF-1α in TAMs reinforces the M2 features and attenuates the cytotoxic effect towards tumor cells." (PMID 37740232, 2023). "All of the analyzed tumor slices from three different xenograft tumors in the MF system showed a gradient for HIF1 α, γH2AX, and CC3." (PMID 36899943, 2023). "Further studies also showed that HPV16 E6 contributed to the HIF-1α-induced Warburg effect by attenuating the von Hippel–Lindau tumor suppressor-HIF-1α interaction." (PMID 37350944, 2023). "A similar phenomenon takes place during the progression of ccRCC, where HIF-2α eventually predominates over HIF-1α to promote tumor growth and metastasis." (PMID 36831657, 2023). "HIF1α stimulates angiogenesis, which provides oxygen and nutrients to the tumor and upregulates its ability to take up glucose for glycolysis, which in turn provides energy for further angiogenesis and cell proliferation." (PMID 37651203, 2023). "Here, we confirmed that treating tumor cells with CVM-1125 reduced the downstream factors of TRAP1 including HIF-1α, Nodal, and Notch." (PMID 37351538, 2023). "HIF-1α–knockdown DCs were less potent in suppressing tumor growth and inducing tumor-infiltrating IFN-γ–producing T cells." (PMID 36821379, 2023). "HIF1α inhibitor has a strong anti-tumor function, and combined with ibrutinib can induce cytotoxicity." (PMID 37790761, 2023).